U6 (U6 spliceosomal RNA )
Synonyms: LOC124900886
Gene: Small nuclear RNA gene on chromosome 4 (48,109,353 to 48,109,410, reverse strand). Ensembl gene ENSG00000283499.
Gene Ontology:
Molecular function: U4 snRNA binding
Biological process: formation of quadruple SL/U4/U5/U6 snRNP; spliceosomal tri-snRNP complex assembly
Cellular component: U4/U6 x U5 tri-snRNP complex; U6 snRNP
Homologues: Orthologues: dog U6 (90% identical), guinea pig U6 (78% identical). Paralogues in human: RNU6-1024P (95% identical), RNU6-1060P (93% identical), RNU6-15P (93% identical), RNU6-19P (93% identical), RNU6-429P (93% identical), RNU6-820P (93% identical), RNU6-906P (93% identical), RNU6-98P (93% identical), RNU6-1 (91% identical), RNU6-1048P (91% identical), RNU6-1091P (91% identical), RNU6-1127P (91% identical), and 1283 more.